IL10 (interleukin 10)
Diseases named in the same sentence as IL10 in open-access papers (continued):
Sharing a sentence is not in itself a finding about the gene and the disease.
ovarian tumor (continued). "Both qPCR and ELISA results showed a reduced expression of anti-inflammatory cytokines including IL-4, IL-10 and TGF-β in murine ovarian tumor after DSF treatment." (PMID 37305383, 2023). "In human ovarian tumors, it is demonstrated that plasmacytoid DCsinduce IL-10 secreting CD8+ regulatory T cells capable of suppressing antitumorimmunity through IL-10." (PMID 18317534, 2007). "In the presence of ovarian tumor ascites CD14+ cells, which expressed IDO and IL-10, CD4+ T cells showed inhibition in responsiveness to antigen stimulation, suggesting IDO and IL-10 might be involved in the regulation of the immune response in EOC." (PMID 31829231, 2019). "The immune-suppressive environment in the ovarian tumor, rich in TGF-β, IL-10, VEGF, ARG-1, along with inhibitory molecules such as IDO, PD-1, and PD-L1, drives the differentiation of CD14+CD1a- immature myeloid cells, anergic T cells and Tregs, induces tolerance, and promotes tumor growth." (PMID 30200478, 2018).
bronchiolitis (16 papers, 2009 to 2025). Inflammation of the bronchioles characterized by swelling of the bronchioles and mucus accumulation. "Nonetheless, in infants below 3 months of age, high IL-10 levels were reported in those with severe bronchiolitis, therefore being considered as a hallmark of disease." (PMID 30936869, 2019). "Impulse oscillometry presented as Z-scores in relation to IL-10 rs1800896 polymorphism in 99 children under the age of seven after hospitalisation for bronchiolitis at less than six months of age." (PMID 26473365, 2015). "Impulse oscillometry presented as Z-scores in relation to IL-10 rs1800871/rs1800872 polymorphisms in 99 children under the age of seven after hospitalisation for bronchiolitis at less than six months of age." (PMID 26473365, 2015). "We used impulse oscillometry (IOS) to evaluate the associations of IL10 polymorphisms with lung function at a median age of 6.3 years in children hospitalised for bronchiolitis before six months of age." (PMID 26473365, 2015). "The main results of this post-bronchiolitis lung function study at a median age of 6.3 years were that IL10 polymorphisms rs1800896, rs1800871, rs1800872 and rs1800890 were associated with lung function measured with IOS." (PMID 26473365, 2015). "Impulse oscillometry presented as Z-scores in relation to IL-10 rs1800890 polymorphism in 98 children under the age of seven after hospitalisation for bronchiolitis at less than six months of age." (PMID 26473365, 2015). "Clinical studies have documented that certain polymorphisms in the gene encoding the regulatory cytokine IL-10 are associated with the development of severe bronchiolitis in RSV infected infants." (PMID 21829368, 2011). "Similarly, increased IL-10 levels in undiluted nasopharyngeal aspirates have been associated with physician-diagnosed post-bronchiolitis wheezing one year after infection." (PMID 40430746, 2025). "Low-IL-10-producing polymorphisms in the IL-10 encoding gene were associated with obstructive lung function parameters, suggesting an important role for IL-10 in development of lung function deficit in early bronchiolitis patients." (PMID 26473365, 2015). "Interestingly, children homozygous for the IL-10 -592C, -592A or IL-10 -1082A allele have had a high risk of severe bronchiolitis." (PMID 19781072, 2009). "Analyzing Th1 cytokines, such as IFN-γ and TNF-a, and Th2 cytokines, such as IL-4, IL-6, and IL-10, presents a challenge in elucidating the immune mechanisms in lung tissue during acute viral bronchiolitis." (PMID 40430746, 2025). "Taken together, all these data highlight the possibility of differentiating bronchiolitis endotypes depending on the virus type and signature cytokine profiles determined by the host genome, including IL-10." (PMID 40430746, 2025). "Our data provide evidence of the substantial role of IL-10 in differentiating endotypes of bronchiolitis, potentially contributing to personalized treatment." (PMID 40430746, 2025). "In the case of hospitalized infants under 3 mo of age, severe bronchiolitis is frequently correlated with the presence of IL10-secreting B cells (Bregs) in nasopharyngeal aspirates, dampening Th1 cytokine production." (PMID 36561744, 2022). "In this sense, it has been proposed that elevated levels of IL6, IFNγ and IL10 among others, protect against hypoxia in bronchiolitis." (PMID 36561744, 2022). "In our study, we demonstrated that the levels of IL-33 and Th2-related cytokines IL-4 and IL-10 in RSV infected acute bronchiolitis in serum of infants were significantly increased." (PMID 34395633, 2021). "Acute bronchiolitis elicited increased levels of IL-4 and IL-10 but decreased level of IFN-γ and IL-2." (PMID 34395633, 2021). "Measurements by NS demonstrated that relative to both RSV− bronchiolitis and healthy control subjects, RSV+ bronchiolitis was associated with higher levels of IFN-γ, IL-1β, CCL5/RANTES, and IL-10 (respectively) (P < .05 throughout)." (PMID 28368490, 2017).
bronchiolitis (continued). "Nasosorption (but not NPA) levels of interferon γ, interleukin 1β, CCL5/RANTES, and interleukin 10 (IL-10) were elevated in RSV+ bronchiolitis (all P < .05), furthermore CCL5 and IL-10 correlated with RSV load (P < .05)." (PMID 28368490, 2017). "Combined IL-10 rs1800896, rs1800871 and rs1800872 genotypes and haplotype frequencies of 99 children hospitalised for bronchiolitis in infancy." (PMID 26473365, 2015). "Impulse oscillometry presented as Z-scores in relation to IL-10 rs1800896, rs1800871 and rs1800872 haplotype carriage in 99 pre-school-aged children after hospitalization for bronchiolitis in infancy." (PMID 26473365, 2015). "Impulse oscillometry presented as Z-scores in relation to combined IL-10 rs1800896, rs1800871 and rs1800872 genotypes in 99 children under the age of seven after hospitalisation for bronchiolitis in infancy." (PMID 26473365, 2015). "This preliminary evidence of cytokine-associated lung function disorder after viral bronchiolitis might reflect the impact of the infection itself during the first months of life or result from a predisposition to a subsequent disease processes in individuals with low IL-10 production." (PMID 26473365, 2015). "Regardless of the viral type, high IL-10 levels were associated with bronchiolitis recurrence (p = 0.021; Mann–Whitney test)." (PMID 40430746, 2025). "Monitoring IL-10 in hospitalized children with acute bronchiolitis may help differentiate the clinical phenotype and implement a specific therapeutic strategy to prevent further development of wheezing and asthmatic responses in infants." (PMID 40430746, 2025). "In addition, a prior study observing the cytokine responses from ILC2s showed diminished cytokine levels of IFN-γ and IL-10 in children with recurrent wheezing compared to children with viral bronchiolitis." (PMID 38932217, 2024). "However, some studies have identified differences in IL-10 concentrations between symptom severities; for example, IL-10 was significantly increased in the NPAs of the acute bronchiolitis (AB) group compared those who developed a more moderate URTI." (PMID 35406717, 2022). "The literature search for this review yielded some targeted studies of certain SNPs, particularly greater frequencies of IL-10 polymorphisms in RSV and bronchiolitis cohorts compared to control groups of both healthy infants and infants with less severe disease." (PMID 35406717, 2022). "This suggested a negative correlation between IL-10 concentration and bronchiolitis severity, but overall associations between IL-10 protein levels and SNPs were not reported." (PMID 35406717, 2022). "However, the data concerning the effects of IL-10 in bronchiolitis are contradicting." (PMID 38932217, 2024). "We found significantly higher IL-10 levels in the RSV-positive group of patients compared to the RV-positive groups and the other groups with viral bronchiolitis." (PMID 40430746, 2025). "We found a significantly higher level of IL-10 in the RSV-positive group of patients than in the RV-positive group and the other groups with viral bronchiolitis." (PMID 40430746, 2025). "Here we show that elevated levels of pro-inflammatory cytokines (IL1β, IL6, TNFα, IL18, IL23), regulatory cytokines (IL10, IL17A) and IFNγ were found in the three bronchiolitis cohorts." (PMID 36561744, 2022). "It was reported that the production of Th2 cytokines IL-4 and IL-10 was promoted by IL-33, and Th2 immune response was described to influence the pathogenesis of respiratory syncytial virus (RSV) acute bronchiolitis." (PMID 34395633, 2021). "The most recent study has suggested a correlation between local IL-10 levels during the initial RSV infection and post-bronchiolitis wheeze, providing further evidence of the importance of IL-10 during human RSV bronchiolitis." (PMID 22393401, 2012).
bronchiolitis (continued). "The total serum IL-10 levels were significantly enhanced in RSV-infected children compared to those infected with RV (14.4 (12.2–24.0) vs. 8.9 (7.2–12.5); p < 0.001) and the other viral bronchiolitis groups (14.4 (12.2–24.0) vs. 6.65 (3.9–15.3); p = 0.003)." (PMID 40430746, 2025). "In summary, bronchiolitis NLF displayed a pronounced pro-inflammatory cytokine profile, and the presence of the regulatory cytokines IL10 and IL17A, in the context of a predominant pro-inflammatory response suggests they participate in the local control of immunopathological injury." (PMID 36561744, 2022). "Although previous studies (from nasal swabs) have shown differences in IFN-γ and IL-10 expression between children infected with RV and RSV, one recent study showed that this difference dissipated when RV-bronchiolitis and RSV-bronchiolitis are accompanied by wheezing." (PMID 36451824, 2022). "Contrastingly, IL-10 was not significantly increased in the acute bronchiolitis (AB) cohort in the first few days of infection before declining to below the URTI cohort levels." (PMID 35406717, 2022). "Notably, IL-10 is not only detectable in the mouse model of RSV but also in nasopharyngeal secretions and serum of infants with severe bronchiolitis." (PMID 22393401, 2012). "Our findings thus provide a cellular and mechanistic link to earlier clinical studies which implicate IL-10 in the pathogenesis of RSV disease and may provide the groundwork for future studies examining IL-10 as a therapeutic option in the treatment of RSV induced bronchiolitis in young infants." (PMID 21829368, 2011).
Cachexia (16 papers, 2011 to 2026). Severe weight loss, wasting of muscle, loss of appetite, and general debility related to a chronic disease. "The principal finding was that high IL-6 was associated with cachexia and a higher risk of immune-related adverse events, while high IL-10 was associated with cachexia and poor overall survival." (PMID 36831513, 2023). "This phenotype was associated with increased levels of cachexia mediators in particular interleukin-10." (PMID 30061533, 2018). "Studies have found associations with cachexia and polymorphisms in IL-1-β, IL-10, IL-6 and IL-8 genes." (PMID 21934689, 2011). "A IL-10 polymorphism (rs 1800896) is observed to be associated with cachexia in two studies; first with a >10% weight loss in a Scottish gastro-oesophageal cancer population, and recently in a Chinese gastric cancer population." (PMID 21934689, 2011). "However, there was a significant increase in the expression of IL-10, which is associated with the development of cachexia." (PMID 25254959, 2014). "Moreover, a Chinese research group recently published associations with cachexia and SNPs in the IL-6, IL-8 and IL-10 genes." (PMID 21934689, 2011). "This was in line with our previous findings that patients with cachexia were likely to have higher IL-10 and poorer overall survival." (PMID 36831513, 2023). "The IL-10 genotype was reported to correlate with the development of cachexia among patients with gastroesophageal malignancy." (PMID 36831513, 2023). "Administration of rapamycin in these mice prevented the development of cachexia and decreased IL-10 levels, suggesting that the production of pro-cachectic factors are regulated by mTOR." (PMID 30061533, 2018). "Notably, the cachexia-associated, pro-inflammatory TNF was upregulated 2.9-fold after weight loss, while expression of all interleukins (IL1B, IL6, IL10), as well as CCL3 was much lower than in the lean group." (PMID 27900559, 2017). "Of these six cytokines, IL-6, IL-8, IL-10, and IL-15 at baseline, and IP-10 at both baseline and during treatment were significantly higher in patients with cachexia than those without." (PMID 36831513, 2023). "IL-1α, TNF, IL-8, and IL-10 were significantly elevated in cachexia patients but IL-1β and IL-6 were not significantly elevated in the cachexia patients." (PMID 36358681, 2022).
Chlamydia infection (16 papers, 2005 to 2024). "In both lung and FRT Chlamydia infection models, IL-10-deficiency leads to accelerated bacterial clearance." (PMID 38271477, 2024). "Future investigations regarding the role of IL-10 polymorphisms in Chlamydia infections are required." (PMID 34093528, 2021). "This indicates that ENO1 is an essential anti-apoptotic molecule in DCs during chlamydia infection and that IL-10 deficiency that upregulates ENO1 in DCs decreases susceptibility to apoptosis." (PMID 28525970, 2017). "IL10−/− mice have been shown to clear Chlamydia infections at a faster rate than WT mice, and this protective ability of the IL-10−/− mice has been linked with the presence of IL-10−/− DCs." (PMID 28525970, 2017). "Host factors including HLA-DQ and interleukin 10 (IL-10) have been associated with Chlamydia infection." (PMID 16368002, 2005). "However, researchers have different opinions on the association between IL-10 polymorphisms and the outcome of Chlamydia infections." (PMID 34093528, 2021). "Moreover, genetic variations in IL-10 gene may be associated with its different expression and the polymorphisms within IL-10 gene may explain interindividual variation in host immune responses to Chlamydia infection." (PMID 34093528, 2021). "However, further study is needed to address the interplay between TLR3 signaling and IL-10 synthesis in order to better understand how dysregulation of IL-10 synthesis during Chlamydia infection of TLR3-deficient mice leads to more substantial genital tract sequalae." (PMID 29624589, 2018). "Although dendritic cells (DCs) play a significant role in anti-infection immune response, understanding the crosstalk between DCs and IL-10 is essential for elucidating the mechanism of immune escape during Chlamydia infection." (PMID 34093535, 2021). "IL-10 is an important factor for balancing the immune system after Chlamydia infection, and the modulation of its expression in Chlamydia-infected hosts is cautiously performed." (PMID 34093528, 2021). "However, the association of Tregs with IL-10 and DCs during Chlamydia infection remains unknown." (PMID 34093535, 2021). "IL-10 is however also responsible for the severe damage, such as tubal infertility and ectopic pregnancy, induced by Chlamydia infection." (PMID 34093528, 2021). "Overall, we delineate an encompassing role for IL-10 (endogenous and exogenous) in minimizing the excessive inflammatory responses induced by Chlamydia infections." (PMID 32684836, 2020). "Evidence of a role for IL-10 in Chlamydia infections has been obtained from studies in patients and animal models." (PMID 30881362, 2019). "Multiple cell types are capable of producing IL-10 during Chlamydia infection including activated macrophages, dendritic cells, keratinocytes, T and B lymphocytes." (PMID 30881362, 2019). "Herein, using a different setting, we provided results that indicate the induction of IL-10-producing B cells after Chlamydia infection of the male genital tract." (PMID 30881362, 2019). "Based on these findings regarding IL-10’s purported role in suppressing IFN-β, we can extrapolate a similar role for IL-10 in the suppression of IFN-β during Chlamydia infection in TLR3-deficient mice." (PMID 29624589, 2018). "In our ongoing study of the function of IL-10−/− DCs during Chlamydia infection, we observed using 2-DIGE proteomics, the differential expression of the protein ENO1, which was up regulated in IL-10−/− DCs compared to WT DCs." (PMID 28525970, 2017). "The results showed that WT mice that were adoptively transferred with Chlamydia pulsed IL-10−/− and WT DCs were better able to clear their Chlamydia infection compared to mice that were adoptively transferred with Chlamydia pulsed ENO1 knockdown DCs." (PMID 28525970, 2017).
Chlamydia infection (continued). "IL-10, upregulated 150-fold by Chlamydia infection, is a key immune regulator during infection with various pathogens, including bacteria, viruses and protozoa; evidence here also indicated a prospective regulatory role in Chlamydia infection of iPSDMs." (PMID 28440293, 2017). "A variety of cells could be responsible for secreting these cytokines: for example, monocytes, dendritic cells and B cells have each been identified as potential sources of IL-10 following Chlamydia infection." (PMID 37862368, 2023). "Moreover, elucidating the mechanism by which the IL-10-mediated NLRP3 inflammasome functions is essential for understanding of Chlamydia infection." (PMID 34093535, 2021). "Inflammatory processes are responsible for complications induced by Chlamydia infections, and IL-10 is hypothesized to be involved in the processes." (PMID 34093528, 2021). "Consequently, a better understanding of signaling events will provide insight into the molecular mechanisms of IL-10-mediated reduction of inflammatory responses during an early Chlamydia infection." (PMID 32684836, 2020). "This supports a role for IL-10 in limiting Chlamydia infections of macrophages." (PMID 28440293, 2017). "The role of IL-10/IL-10R signalling in Chlamydia infection is likely to be complex." (PMID 28440293, 2017). "Therefore, understanding the role of IL-10 is essential for the control of Chlamydia infection." (PMID 34093535, 2021). "Thus, cumulative data indicate that IL-10 has a critical role during Chlamydia infection." (PMID 30881362, 2019). "Consistent in part with this, at 24 h post Chlamydia infection, human iPSdMs were shown, using Luminex bead-based multiplex assays, to express high levels of the pro-inflammatory cytokines IL-6 and TNFα, as well as IL-1β, chemokine IL-8 and the anti-inflammatory cytokine IL-10." (PMID 28440293, 2017). "Overall, these data showed a decreased IL-12 production, but a higher IL-10 production pattern in DCs of SND1-/- mice, especially with chlamydia infection." (PMID 33635920, 2021). "Since cellular immunity is a key component of the protective immune response following Chlamydia infection, we evaluated the magnitude of Th1 (IFN-γ, IL-2, IL-12, IL-18), Th2 (IL-4) and anti-inflammatory (IL-10) cytokines (Expt." (PMID 34001988, 2021). "Chlamydia infection consistently coincided with the lack of IL10 and TGFβ expressing cells, conversely to the vaccination groups, indicating vaccination upregulates an anti-inflammatory/tissue repair type response." (PMID 36799886, 2023). "IL-10 nanoparticle capsules as therapeutic strategies can modulate the release of IL-6, IL-12p40, suppressor of cytokine signaling 1 (SOCS1), and SOCS3 by mitigating the inflammatory response against Chlamydia infection in macrophages." (PMID 34093535, 2021). "We later validated this through Western blotting and confocal microscopy analysis, where we showed that ENO1 expression decreased with time in WT DCs during Chlamydia infection, however, the levels of ENO1 in IL-10−/− DCs remained consistently high all through." (PMID 28525970, 2017).